SLC25A42 (solute carrier family 25 member 42)
Description:
Mitochondrial carrier mediating the transport of coenzyme A (CoA) in mitochondria in exchange for intramitochondrial (deoxy)adenine nucleotides and adenosine 3',5'-diphosphate.
Synonyms: MGC26694; MECREN
Tractability: Antibody: UniProt predicts a signal peptide or a membrane-spanning region. PROTAC: its protein half-life has been measured.
Gene: Protein-coding gene on chromosome 19 (19,061,697 to 19,113,030, forward strand). Ensembl gene ENSG00000181035.
Subcellular location: Mitochondrion inner membrane
Subcellular location (Human Protein Atlas): Mitochondria
Pathways (Reactome):
Metabolism: Vitamin B5 (pantothenate) metabolism
Gene Ontology:
Molecular function: ADP phosphatase activity; ADP transmembrane transporter activity; AMP transmembrane transporter activity; ATP transmembrane transporter activity; ATP:ADP antiporter activity; coenzyme A transmembrane transporter activity; protein binding; nucleobase-containing compound transmembrane transporter activity; organophosphate ester transmembrane transporter activity
Biological process: ADP transport; AMP transport; ATP transport; coenzyme A transmembrane transport; mitochondrial coenzyme A transmembrane transport; pantothenate metabolic process; transmembrane transport
Cellular component: mitochondrial inner membrane; mitochondrion; nucleus
Genetic constraint (gnomAD): Loss-of-function variants: 19 observed, 32.12 expected, observed/expected ratio (o/e) 0.59, 90% interval 0.41 to 0.87. The upper end of that interval is the gene's LOEUF score, 0.87, which puts it in group 3 of 6, group 1 being the genes least tolerant of losing a copy. Missense variants: 363 observed, 434.42 expected, observed/expected ratio (o/e) 0.84, 90% interval 0.77 to 0.91. Synonymous variants: 205 observed, 194.75 expected, observed/expected ratio (o/e) 1.05, 90% interval 0.94 to 1.18.
Homologues: Orthologues: chimpanzee SLC25A42 (100% identical), macaque SLC25A42 (99% identical), pig SLC25A42 (93% identical), mouse Slc25a42 (92% identical), rat Slc25a42 (91% identical), guinea pig SLC25A42 (91% identical), tropical clawed frog slc25a42 (77% identical), zebrafish slc25a42 (75% identical), dog SLC25A42 (65% identical), Drosophila melanogaster DPCoAC (53% identical), Caenorhabditis elegans slc-25A42 (49% identical). Paralogues in human: SLC25A16 (38% identical), SLC25A13 (27% identical), SLC25A25 (26% identical), SLC25A12 (26% identical), SLC25A23 (25% identical), SLC25A24 (25% identical), SLC25A4 (24% identical), SLC25A6 (23% identical), SLC25A5 (23% identical), SLC25A1 (22% identical), SLC25A31 (22% identical), SLC25A17 (22% identical), and 37 more.
Diseases named in the same sentence as SLC25A42 in open-access papers:
SLC25A42 is named in the same sentence as 25 diseases in open-access papers, as found by Europe PMC text mining. Sharing a sentence is not in itself a finding about the gene and the disease. The quoted sentences say what the papers report.
Mitochondrial myopathy (5 papers, 2020 to 2025). "Mutations in SLC25A42 have been associated with mitochondrial myopathy and encephalomyopathy in humans, highlighting the importance of SLC25A42 in normal physiological functions." (PMID 40246810, 2025). "Recently, one SLC25A42 variant was found in different patients with variable clinical features attributable to mitochondrial myopathy." (PMID 34827632, 2021). "A bi‐allelic deleterious (c .871A > G, p.Asn291Asp) SLC25A42 variant was first described as a cause of mitochondrial myopathy in a 16‐year‐old boy born to consanguineous Saudi parents." (PMID 34258143, 2021).
lactic acidosis (3 papers, 2019 to 2024). Metabolic acidosis characterized by the accumulation of lactate in the body. "SLC25A42 deficiency leads to a congenital disease with a heterogeneous clinical presentation, including myopathy, developmental delay, lactic acidosis, and encephalopathy." (PMID 39512436, 2024).
Encephalopathy (2 papers, 2020 to 2024). Encephalopathy is a term that means brain disease, damage, or malfunction. "Recessive variants in SLC25A42 induce a variety of clinical features and disease onset, from isolated myopathy to combinations of movement disorders, encephalopathy, seizures, and developmental regression." (PMID 33426505, 2020). "Recessive variants in SLC25A42 induce a variety of clinical features and range from isolated myopathy to movement disorders, encephalopathy, seizures, and developmental regression in other patients." (PMID 33426505, 2020).
mitochondrial encephalomyopathy (2 papers, 2021 to 2025). A heterogenous group of disorders characterized by alterations of mitochondrial metabolism that result in muscle and nervous system dysfunction. "In conclusion, we report additional patients with SLC25A42‐associated mitochondrial encephalomyopathy." (PMID 34258143, 2021). "In conclusion, we report six additional patients with SLC25A42‐associated mitochondrial encephalomyopathy." (PMID 34258143, 2021). "Notably, the homozygous N291D mutation in SLC25A42 has been shown to cause mitochondrial encephalomyopathy." (PMID 41279021, 2025). "Finally, DBS should be considered in the management of patients with SLC25A42‐associated mitochondrial encephalomyopathy and life altering dystonia." (PMID 34258143, 2021). "To date, 15 individuals have been reported to have one of two bi‐allelic homozygous missense variants in the SLC25A42 as the cause of mitochondrial encephalomyopathy, of which 14 of them were of Saudi origin and share the same founder variant, c.871A > G:p.Asn291Asp." (PMID 34258143, 2021).
placental insufficiency (2 papers, 2020 to 2021). Failure of the placenta to deliver an adequate supply of nutrients and oxygen to the fetus. "Little is known about the role of SLC25A42 in response to the chronic hypoxia and nutrient deprivation associated with placental insufficiency." (PMID 32984199, 2020). "It is essential to emphasize that, because of the small cohort size in this feasibility study, the role of SLC25A42 as a potential transcriptional biomarker for placental insufficiency requires further confirmation with a larger study." (PMID 32984199, 2020). "SLC25A42, a gene belonging to the soluble carrier family responsible for coenzyme-A and adenosine 3′,5′-diphosphate transport in human mitochondria, was thus found to be differentially upregulated in the placental insufficiency group." (PMID 33668810, 2021). "We demonstrated that SLC25A42 was differentially expressed when comparing the placental insufficiency group to the preeclampsia and the control groups, but not when comparing the preeclampsia group to the control group." (PMID 33668810, 2021).
gastric cancer (1 paper, 2025). A primary or metastatic malignant neoplasm involving the stomach. "This study focused on the roles and mechanisms of SLC25A42 in the metabolism and malignant properties in gastric cancer cells." (PMID 40246810, 2025). "Moreover, SLC25A42 expression was also found to be higher in a serial of human gastric cancer cell lines (SNU-638, MKN-1, HGC-27, MKN-45, SNU-216) in comparison to primary human normal gastric cells (GES-1)." (PMID 40246810, 2025). "Although SLC25A42 has been recognized as a mitochondria-localized protein by MitoCarta3.0 database, its expression in gastric cancer cells remains unknown." (PMID 40246810, 2025). "SLC25A42 promotes the growth of gastric cancer (GC) cells while suppresses ferroptosis by reprograming lipid metabolism through elevating the acetylation and thus expression of CPT2, implying that SLC25A42 could serve as a potential therapeutic strategy for the treatment of this malignancy." (PMID 40246810, 2025). "SLC25A42 promotes the proliferation of gastric cancer (GC) cells while suppresses apoptosis in vitro and in vivo." (PMID 40246810, 2025).
lung carcinoma (1 paper, 2021). "SLC25A42, AMT, and IVD genes have also been found in other prognostic models of lung cancer." (PMID 34539973, 2021). "In addition, our model screened several genes that have not been studied in the field of lung cancer but are closely related to the prognosis of LUAD patients, such as SLC25A42, AMT, and IVD, which provides a basis for future research on the mechanism of lung cancer." (PMID 34539973, 2021).
tumor (3 papers, 2022 to 2025). "Additionally, GC patients exhibiting larger tumor size and advanced stages were associated with markedly increased SLC25A42 expression." (PMID 40246810, 2025). "Furthermore, ADAMTS8 and SLC25A42 encode for proteins with strong antiangiogenic effects and antiproliferative properties, respectively, with decreased expression associated with increased tumor viability and proliferation." (PMID 39766155, 2024). "To clarify the biological functions of SLC25A42 in vivo, we established subcutaneous tumor models in the nude mice." (PMID 40246810, 2025). "Moreover, we found that the expressions of SLC25A42 and CPT2 were positively associated in tumor tissues from GC patients." (PMID 40246810, 2025). "Similarly, downregulated genes identified in Cluster 1 have been previously associated with more aggressive tumor characteristics and higher tumor grade; these include RNF39, ADAMTS8, SLC25A42, ST3GAL5, and ZBED3." (PMID 39766155, 2024). "As shown, of the various tumor pathological grades, the expression levels of SLC25A4 (P < 0.01), SLC25A11 (P < 0.0001), SLC25A24 (P < 0.01), SLC25A37 (P < 0.01), SLC25A42 (P < 0.01), SLC25A43 (P < 0.0001), SLC25A44 (P < 0.05) and SLC25A45 (P < 0.05) were significantly different." (PMID 36514121, 2022). "Consistently, IHC staining in xenograft tumor tissues from nude mice models indicated increased level of 4-hydroxy-2-noneal (4-HNE), which is a lipid peroxidation marker, when SLC25A42 was silenced." (PMID 40246810, 2025).
cancer (1 paper, 2025). A tumor composed of atypical neoplastic, often pleomorphic cells that invade other tissues. "Our data highlights SLC25A42 as a crucial suppressor of ferroptosis by activating FAO in cancer cells." (PMID 40246810, 2025). "However, the biological roles of SLC25A42 in human cancers are still unexplored." (PMID 40246810, 2025). "However, the influence of SLC25A42 on cellular metabolism remains largely unknown, especially in human cancer cells." (PMID 40246810, 2025). "However, the biological roles of SLC25A42 in human cancer progression are still unexplored." (PMID 40246810, 2025).
SLC25A42 also shares sentences with these, for which no sentence is quoted: encephalomyopathy (3 papers); myopathy (3); alcohol dependence (2); Alzheimer disease (2); Anxiety (2); dementia (2); depression (2); developmental delay (1); Dystonia (1); Epileptic encephalopathy (1); lung adenocarcinoma (1); metabolic syndrome (1); movement disorder (1); neurodevelopmental disorder (1); preeclampsia (1); prostate carcinoma (1).